ASZ1 (ankyrin repeat, SAM and basic leucine zipper domain containing 1)
Description:
Plays a central role during spermatogenesis by repressing transposable elements and preventing their mobilization, which is essential for the germline integrity. Acts via the piRNA metabolic process, which mediates the repression of transposable elements during meiosis by forming complexes composed of piRNAs and Piwi proteins and governs the methylation and subsequent repression of transposons. Its association with pi-bodies suggests a participation in the primary piRNAs metabolic process. Required prior to the pachytene stage to facilitate the production of multiple types of piRNAs, including those associated with repeats involved in the regulation of retrotransposons. May act by mediating protein-protein interactions during germ cell maturation (By similarity).
Synonyms: ALP1; ANKL1; C7orf7; GASZ; Orf3; CT1.19
Tractability: No criterion of Open Targets' tractability assessment is met for any kind of drug.
Gene: Protein-coding gene on chromosome 7 (117,363,222 to 117,428,123, reverse strand). Ensembl gene ENSG00000154438.
Subcellular location: Cytoplasm
Subcellular location (Human Protein Atlas): Cytosol; Nucleoplasm
Pathways (Reactome):
Gene expression (Transcription): PIWI-interacting RNA (piRNA) biogenesis
Gene Ontology:
Molecular function: protein binding
Biological process: male meiotic nuclear division; spermatogenesis; transposable element silencing
Cellular component: cytoplasm; pi-body; cytoplasmic ribonucleoprotein granule
Genetic constraint (gnomAD): Loss-of-function variants: 33 observed, 33.83 expected, observed/expected ratio (o/e) 0.98, 90% interval 0.74 to 1.3. The upper end of that interval is the gene's LOEUF score, 1.3, which puts it in group 5 of 6, group 1 being the genes least tolerant of losing a copy. Missense variants: 393 observed, 386.71 expected, observed/expected ratio (o/e) 1.02, 90% interval 0.94 to 1.11. Synonymous variants: 140 observed, 141.16 expected, observed/expected ratio (o/e) 0.99, 90% interval 0.86 to 1.14.
Homologues: Orthologues: chimpanzee ASZ1 (99% identical), macaque ASZ1 (97% identical), rabbit ASZ1 (89% identical), dog ASZ1 (88% identical), pig ASZ1 (88% identical), mouse Asz1 (85% identical), guinea pig ASZ1 (83% identical), tropical clawed frog asz1 (50% identical), zebrafish asz1 (36% identical). Paralogues in human: ANKRD34C (16% identical).
Diseases named in the same sentence as ASZ1 in open-access papers:
ASZ1 is named in the same sentence as 27 diseases in open-access papers, as found by Europe PMC text mining. Sharing a sentence is not in itself a finding about the gene and the disease. The quoted sentences say what the papers report.
Infertility (4 papers, 2009 to 2022). "Furthermore, a study describing the conditional loss of Nrf1 in testis implicated the loss of Asz1 (Gasz1) transcription as a causative factor in the infertility of these mice." (PMID 31350280, 2019).
ASZ1 also shares sentences with these, for which no sentence is quoted: infection (64 papers); viral infection (25); COVID-19 (6); tumor (6); hepatoma (3); adenovirus infection (2); cancer (2); co-infection (2); Hepatitis (2); male infertility (2); obstructive jaundice (2); acute pneumonia (1); Azoospermia (1); Cirrhosis (1); cryptorchidism (1); encephalitis (1); herpesvirus infection (1); hypogonadotropic hypogonadism (1); lipid metabolic disorder (1); lung carcinoma (1); melanoma (1); monocytic leukemia (1); myeloma (1); ovarian carcinoma (1); staphylococcus aureus infection (1); systemic lupus erythematosus (1).